FCGR2A (Fc gamma receptor IIa)
Diseases named in the same sentence as FCGR2A in open-access papers (continued):
Sharing a sentence is not in itself a finding about the gene and the disease.
cancer (41 papers, 2012 to 2025). A tumor composed of atypical neoplastic, often pleomorphic cells that invade other tissues. "FCGR2A-dependent activation has been implicated to mediate immuno-thrombosis across multiple cancers via interacting with the platelet integrin αIIbβ3, though not yet in NSCLC." (PMID 41226816, 2025). "Only limited reports pointed out that high expression of FCGR2A was associated with a poor prognosis for cancer patients." (PMID 38022584, 2023). "Evidence for the relevant role of neutrophils in this cancer type comes from the favorable correlation with clinical outcome found after anti-GD2 immunotherapy with a specific polymorphic variant of FCGR2A." (PMID 34503071, 2021). "The FCGR2A gene, a member of the gene family encoding the immunoglobulin Fc receptor, regulates antibody-dependent cytotoxicities, which are essential for the elimination of cancer cells." (PMID 36704353, 2022). "Extensive data points toward the fact that patients with higher-affinity FCGR2A-p.166His or FCGR3A-p.176Val alleles have an enhanced response to monoclonal antibody-mediated anti-cancer therapy amongst solid tumors of the breast, head and neck, colorectal carcinomas as well as lymphomas." (PMID 31632391, 2019). "Taken together, our integrative strategy revealed ITGA2B, FLNA, GRB2, FCGR2A, and APP as high-confidence, FDA-targetable candidates that intersect cancer-associated platelet education with pro-metastatic platelet signaling." (PMID 41226816, 2025). "All cancer cell lines exhibited elevated FCGR2A expression, with the highest level observed in SNU-878 cells (p < 0.01), which were therefore selected for subsequent functional assays." (PMID 41208969, 2025). "The results showed that CD274 and FCGR2A proteins have been identified as possible cancer therapeutic targets, indicating the potential and importance of these proteins in anti-cancer drug development." (PMID 39857814, 2025). "Initial studies supported that the alleles encoding the high‐affinity alleles FCGR2A‐131H and FCGR3A‐158V significantly augment cancer patient responses and outcomes to mAb‐based regimens." (PMID 39345014, 2024). "To determine the crucial molecular relationships of FCGR2A, we conducted a pan-cancer analysis on this oncogene." (PMID 38237211, 2024). "At present, there are few studies regarding the FCGR2A gene, and its function in cancer is still uncertain." (PMID 35664780, 2022). "In the GEPIA website, we compared the expression of FCGR2A in the adjacent cancer tissues and the cancer tissues." (PMID 34285919, 2021). "Our data showed that FCGR2A expression was correlated with the expression of 21 immune markers in the HNSC samples, while in the adjacent cancer tissues, the expression of FCGR2A was correlated with 16 immune markers." (PMID 34285919, 2021). "In the HNSC patients with HPV negativity, the expression of FCGR2A in cancer tissues was higher than that of the adjacent tissues." (PMID 34285919, 2021). "This contributed to the illustration on the roles of the FCGR2A gene in radiotherapy resistance among carcinomas of nasopharynx patients." (PMID 34285919, 2021). "FCGR2A expression in several carcinoma tissues was significantly higher than that of adjacent tissues." (PMID 34285919, 2021). "Three candidate genes (ALOX5AP, CD74, and FCGR2A) were found, all of which were expressed at higher levels in lungs and lymph nodes than in matched cancer tissues and were probably expressed in the microenvironment." (PMID 31992246, 2020). "CD74 mRNA in brain, retina, lung, and lymph nodes displayed higher levels than in the matched cancer tissues, while FCGR2A mRNA in thyroid, lung, kidney, peritoneum, and lymph node tissues displayed higher levels than in the matched cancer tissues." (PMID 31992246, 2020).
cancer (continued). "Targeting cancer-derived IgG or blocking FCGR2A could potentially hinder TEP-mediated metastasis and may offer a novel therapeutic strategy for inhibiting cancer-induced platelet activation while minimizing disruption to normal hemostatic processes." (PMID 41226816, 2025). "We chose 12 cancers from the database, all of which expressed FCGR2A." (PMID 38319156, 2024). "Therefore, we applied the pan-cancer analysis to unravel the principal pathways of FCGR2A and its interaction in the immune landscape." (PMID 38237211, 2024). "The expression of FCGR2a is increased in several carcinoma tissues." (PMID 37892617, 2023). "Interestingly, in those with grade 4 cancer, the expression of FCGR2A showed a decline in all the 7 cases." (PMID 34285919, 2021). "In the adjacent cancer tissues, the expression of FCGR2A was correlated with 16 immune markers." (PMID 34285919, 2021). "Differences in IgG1 affinity to FCGR2A- H131 and FCGR2A- R131 are negligible and therefore may lack functional consequence, however, they have still been compared in response to anti-cancer mAb treatment." (PMID 37652365, 2023). "Across all methods, we observed convergence on FCGR2A and APP as key targets, supporting their robust involvement in cancer–platelet signaling." (PMID 41226816, 2025). "There is also uncertainty regarding the influence of FCGR2A H131R and FCGR2B T232 in anti-cancer therapy." (PMID 37652365, 2023). "SNPs in FCGR2A and FCGR3A genes influencing mAb affinity for FcγR have previously been shown to modify antibody immunotherapy in cancer patients." (PMID 30899264, 2019). "The log fold changes and, thus, the rankings among all the DEGs are almost the same for each of the found key genes ITGA2B, FLNA, GRB2, FCGR2A, and APP across all three datasets, confirming that these are consistently differentially expressed in NSCLC vs. healthy/non-cancer." (PMID 41226816, 2025). "Drugs targeting TNFRSF9, IL2RA, FCGR2A, IFNGR2 were found to be potential targets for cancers." (PMID 36857861, 2023). "Likewise, cancer grades analysis by TISIDB indicated that mRNA expressions of FCGR1A/B, FCGR2A/B/C, and FCGR3A correlated with cancer grade of ccRCC." (PMID 35372055, 2022). "Consequently, we believe alternative TEPs mRNAs, including RSL24D1, IFI27, CRYM, HBD, IFITM3, FCGR2A, and KLHDC8B mRNA, can potentially serve as non‐invasive biomarkers for diagnosing cancers and can even predict the prognosis of pan‐cancer." (PMID 33955587, 2021). "In this study, 7 TEPs mRNAs were verified, including RSL24D1, IFI27, CRYM, HBD, IFITM3, FCGR2A, and KLHDC8B, which may be used for cancer detection." (PMID 33955587, 2021). "Seven TEPs mRNAs were discovered in our study: RSL24D1, IFI27, CRYM, HBD, IFITM3, FCGR2A, and KLHDC8B in TEPs, which are mainly enriched in protein binding, extracellular matrix, and metabolic process, and may be used for cancer diagnosis." (PMID 33955587, 2021). "While many studies have reported associations between the high affinity FCGR2A and FCGR3A alleles and greater mAb efficacy in numerous cancers, others have not observed such associations, perhaps due to differing and complex biological backgrounds." (PMID 30899264, 2019). "In addition, we also found that the presence of HDAC7 led to the upregulation of genes related to immune processes (IL16, FCGR2A, IRAK2, CD86 and CD40, among others) and cancer (RASSF4, RAB31, NEDD9 and RASSF2, among others)." (PMID 25675295, 2015). "Therefore, our results indicate that FCGR2A, PDE3A, and EPPK1 are the main target genes for MYBL2 and may function as novel cancer biomarkers." (PMID 35664780, 2022). "Moreover, polymorphisms in the genes coding for the receptors mainly responsible for ADCC, i.e., Fc fragment of IgG, low affinity IIa, receptor (FCGR2A, also known as CD32) and FCGR3A (also known as CD16a), have been shown to influence the response of cancer patients to most tumor-targeting mAbs." (PMID 25537519, 2014).
infection (34 papers, 2010 to 2025). The state of being infected such as from the introduction of a foreign agent such as serum, vaccine, antigenic substance or organism. "We postulated that HIV transmission might be impacted by allelic variation in FCGR3A or FCGR2A, since these are important signaling receptors that will affect immune activation and susceptibility to infection." (PMID 21187939, 2010). "It is suggested that FCGR2A is responsible for the modulation of severity of infection and autoimmune response—it is not only a marker of KD." (PMID 37896870, 2023). "Compared with the EBV-HLH and HLH-other infection group, FCGR2A and CD163 were significantly increased in the HLH-malignancy group." (PMID 37653176, 2023). "Proteomic analysis showed that the expression levels of FCGR2A and CD163 were higher in these patients than in patients with infection-associated HLH." (PMID 37653176, 2023). "Based on these data, we hypothesize that the presence of any meaningful level of infection enhancement gives the virus—DENV-2 in this case—sufficient access to target cells that bear Fc-gamma receptor IIa (CD32a)." (PMID 34021159, 2021). "Moreover, monocyte ADP was found to be a correlate of reduced infection risk in HVTN505 Phase 2b efficacy trial, and SNPs in the FcγRIIa gene (FCGR2A) modified this correlation." (PMID 34093580, 2021). "In summary, our work shows that the variation in FCGR2A gene does not influence the risk to be infected with RSV in infants but it is associated with the outcome of the infection." (PMID 33392111, 2020). "Our finding that infant FCGR2A genotype does not impact infant infection risk differs from the one previous study of FCGR2A genotypes in MTCT that observed more infections in infants with the high-affinity receptor." (PMID 26613093, 2015). "We measured abundance of low and high activity alleles in two Fc receptor genes, FCGR2A and FCGR3A, for persons with HIV disease, natural virus suppressors (HIV+, without disease) and healthy controls to show whether genotypes were associated with infection and disease." (PMID 21187939, 2010). "Additionally, the top predicted transcriptional regulators (P < .01) at 2 h post-infection of the pre-treated cells were dextran sulfate, TLR4, kinase EIF2AK3, FCGR2A, and LEP." (PMID 33382951, 2021). "The observation that infant FCGR2A and FCGR3A genotypes do not influence infant infection or disease progression has important implications for treatment and therapy." (PMID 26613093, 2015).
bacterial infections (6 papers, 2006 to 2025). "The NOS3 (rs1799983) G allele and the FCGR2A (rs1801274) G allele were positively correlated with the occurrence of bacterial infections in patients; β = 1.96, OR = 7.12, p value = 0.0212; and β = 1.68, OR = 5.4, p value= 0.014, respectively." (PMID 37630611, 2023). "This SNP has been shown to play a role in the susceptibility to bacterial infections as FCGR2A [131H/H] individuals have greater potential to mediate IgG2-dependent bacterial phagocytosis than patients genotyped as FCGR2A [131R/R]." (PMID 31249568, 2019). "FCGR2A-131H is, therefore, essential for handling IgG2 immune complexes: individuals homozygous for the 131R-allele have been shown to have an increased susceptibility to various encapsulated bacterial infections, such as Neisseria meningitides, Haemophilus influenzae and Streptococcus pneumoniae." (PMID 16846526, 2006). "A positive correlation between the incidence of bacterial infection, and the gain of a mutant allele, was observed for the polymorphisms rs1799983 (NOS3) and rs1801274 (FCGR2A)." (PMID 37630611, 2023). "A positive correlation was detected between bacterial infections and the NOS3 rs1799983 G allele and the FCGR2A rs1801274 G allele." (PMID 37630611, 2023).
infectious disease (3 papers, 2020 to 2025). A disorder directly resulting from the presence and activity of a microbial, viral, or parasitic agent in humans. "Fc gamma receptor IIa (FCGR2A) gene polymorphism is associated with increased susceptibility to autoimmune and infectious diseases." (PMID 40214943, 2025). "Locus 1q23, that harbors the FCGR2A gene, is well known for its association with a variety of autoimmune and infectious diseases." (PMID 33392111, 2020).
FCGR2A also shares sentences with these, for which no sentence is quoted: lymphoma (6 papers); viral infection (5); asthma (4); dengue disease (3); metastatic disease (3); periodontitis (3); type 1 diabetes (3); AIDS (2); carcinoma of the pancreas (2); colon carcinoma (2); coronary artery disease (2); Crohn disease (2); Guillain-Barre syndrome (2); hepatocellular carcinoma (2); multiple sclerosis (2); Parkinson disease (2); pneumococcal infection (2); staphylococcus aureus infection (2); Stroke (2); unstable angina (2); acute myocardial infarction (1); adenoma (1); adrenocortical carcinoma (1); agranulocytosis (1); Allergy (1); atransferrinemia (1); Behcet disease (1); breast neoplasm (1); carcinoma of bile duct (1); carcinoma of the esophagus (1).
A further 63 diseases each share a sentence with FCGR2A in 1 paper.